LRRK2 (leucine rich repeat kinase 2)
Diseases named in the same sentence as LRRK2 in open-access papers (continued):
Sharing a sentence is not in itself a finding about the gene and the disease.
Parkinson disease (continued). "We define how these components are impacted by Parkinson's pathogenic mutations (LRRK2[R1441C] and VPS35[D620N]) and LRRK2 inhibitors." (PMID 33367571, 2021). "Our findings are consistent with noncoding variation in LRRK2 that predisposes to Parkinson’s disease, presumably by altering levels of wild type LRRK2." (PMID 34030727, 2021). "Mutations in LRRK2 are the most common cause of familial Parkinson’s disease and typically cause disease in the context of abnormal aggregation and deposition of α-synuclein within affected brain tissue." (PMID 34030727, 2021). "LRRK2 is the leading cause of inherited Parkinson’s disease, a disorder of the central nervous system that manifests as a progressive degeneration of motor mobility, balance, and tremors." (PMID 33887226, 2021). "LRRK2 parkinsonism has been hailed as the “Rosetta stone” of parkinsonian disorders as brains from LRRK2 cases demonstrate all major pathologies associated with parkinsonism, including a large proportion with concomitant Alzheimer’s pathology." (PMID 33494262, 2021). "The human mutations modeled included the most common Parkinson’s disease-associated mutation in human LRRK2, G2019S (G1914S in Drosophila) and I2020T (11915T in Drosophila)." (PMID 34030727, 2021). "Employing this assay, we are able to quantify the relative abundance of the different pRab proteins in multiple cells and tissues, defining the impact of LRRK2 inhibitors and Parkinson's disease-causing mutations." (PMID 33367571, 2021). "Pathogenic variants in the Leucine-rich repeat kinase 2 (LRRK2) gene are the most common known monogenic cause of Parkinson's disease (PD)." (PMID 34475849, 2021). "We previously established a fly model of PD carrying the LRRK2-G2019S mutation that exhibited the parkinsonism-like phenotypes." (PMID 34779396, 2021). "Looking upon Parkinson’s disease, iPSCs carrying LRRK2 G2019S mutation were isolated from patients to develop human neuroectodermal spheres which showed the synaptic dysfunction pathway to be the most altered pathway in Parkinson’s disease PDOs." (PMID 34299287, 2021). "Parkinson's pathogenic mutations increase LRRK2 protein kinase activity thereby stimulating Rab protein phosphorylation." (PMID 33459343, 2021). "For example, neural stem cells derived from the skin of individuals carrying a mutation associated with Parkinson’s disease in the gene for LRRK2 exhibit increased mitochondrial DNA damage as well as increased oxidative damage." (PMID 32293561, 2020). "The function of LRRK2 has been most intensely studied in human cells because it has been identified as a risk factor for sporadic Parkinson's disease." (PMID 31652367, 2020). "In this study, we employed dopaminergic neurons and microglia differentiated from patient-derived induced pluripotent stem cells carrying LRRK2 G2019S, the most common Parkinson’s disease-associated mutation." (PMID 33057020, 2020). "Pathogenic mutations in the Leucine-rich repeat kinase 2 (LRRK2) are the predominant genetic cause of Parkinson's disease (PD)." (PMID 32601174, 2020). "Mutations in LRRK2 account for approximately 4% of familial and 1% of idiopathic cases of the progressive neurodegenerative disorder, Parkinson's disease (PD), forming an important genetic risk factor for PD." (PMID 32359446, 2020). "Mutations in the leucine‐rich repeat kinase 2 (LRRK2) gene are a common genetic cause of both familial and sporadic Parkinson's disease (PD)." (PMID 32652692, 2020). "Taken together, these data suggest that increased LRRK2 activity is a common pathogenic mechanism in Parkinson’s disease." (PMID 33298952, 2020). "Familiar forms of Parkinson’s disease are linked to mutations in leucine-rich repeat kinase 2 (LRRK2), a gene involved in autophagy among several other functions." (PMID 32260050, 2020). "Mutations of the leucine-rich repeat kinase-2 (LRRK2) gene represent one of the most common genetic causes of Parkinson's disease (PD)." (PMID 32477237, 2020).
Parkinson disease (continued). "The impacts of LRRK2 and its substrate Rab GTPases in the endolysosomal system have also been implicated in the pathomechanism of Parkinson’s and related disorders." (PMID 32256311, 2020). "A growing number of genes associated with Parkinson’s disease are implicated in the regulation of lysosome function, including LRRK2, whose missense mutations are perhaps the most common monogenic cause of this neurodegenerative disease." (PMID 32499675, 2020). "Mutations in LRRK2 (leucine-rich repeat kinase 2) are strongly associated with Parkinson’s disease, and LRRK2 was recently shown to interact with the a1 subunit isoform." (PMID 32656214, 2020). "LRRK2 is also associated with Parkinson’s disease and is involved in vesicle transport, autophagy, cytoskeleton formation and mitochondrial function." (PMID 33224134, 2020). "To confirm the efficiency of NGS-panels designed with the NGS-PrimerPlex tool, we applied it to sequence coding exons of the LRRK2 gene, associated with Parkinson’s disease." (PMID 33378360, 2020). "Parkinson’s disease susceptible genes, which encode for proteins such as leucine-rich repeat kinase 2 (LRRK2), Parkin, PINK1, and DJ-1, are localized on the mitochondria and interfere with the function of mitochondria." (PMID 32655368, 2020). "The Parkinson's disease-associated gene, LRRK2, is also associated with immune disorders and infectious disease and is expressed in immune subsets." (PMID 32359446, 2020). "Research on LRRK2 is mainly focused on the central nervous system and immune system, due to the association with Parkinson’s disease, inflammatory bowel disease, and leprosy." (PMID 32916992, 2020). "Evidence is mounting that LRRK2 function, particularly its kinase activity, is elevated in multiple forms of Parkinson’s disease, both idiopathic as well as familial forms linked to mutations in the LRRK2 gene." (PMID 33013290, 2020). "Drosophila models of Parkinson’s have consistently shown loss of dopaminergic neurons with age when LRRK2, α-synuclein or parkin were manipulated." (PMID 32321836, 2020). "Our findings suggest that Chetomin can be a potential therapeutic compound in LRRK2 linked Parkinson’s disease." (PMID 32990658, 2020). "Mutations in the leucine-rich repeat kinase 2 (LRRK2) gene are the most frequent cause of familial Parkinson’s disease (PD)." (PMID 32765209, 2020). "LRRK2 phosphorylates a set of Rab GTPases in cells, which is enhanced by the Parkinson-associated LRRK2 mutations." (PMID 32256311, 2020). "Discovered in 2004, mutations in the leucine-rich repeat kinase 2 (LRRK2) gene represent one of the most common genetic causes of Parkinson disease (PD), explaining an estimated 1–2% of cases overall." (PMID 32796584, 2020). "A recent study across multiple systems (fly, mouse, and Parkinson's patients) has implicated LRRK2 in phagocytic uptake of beads or E. coli through LRRK2 phosphorylating the actin-remodeling complex component, WAVE2." (PMID 32359446, 2020). "The Y1699C mutant of LRRK2, a pathogenic mutant for Parkinson’s disease, promotes the enlargement of lipid droplets through the phosphorylation of Rab8a in an adipose cell line." (PMID 32916992, 2020). "Mutations in the gene coding for the kinase LRRK2 are the most common genetic cause of inherited Parkinson’s disease." (PMID 32293561, 2020). "Parkinson pathogenic mutations in Lrrk2 increased Rab phosphorylation, which decreased Rab binding to regulatory proteins like guanine nucleotide dissociation inhibitors (GDIs)." (PMID 32033485, 2020). "Transcript levels of LRRK2, a kinase highly associated with Parkinson’s disease, were also upregulated." (PMID 32265286, 2020). "The R1441G mutation in the leucine-rich repeat kinase 2 (LRRK2) gene results in late-onset Parkinson’s disease (PD)." (PMID 33213462, 2020). "LRRK2 mutations cause Parkinson’s, but the molecular link from increased kinase activity to pathological neurodegeneration remains undetermined." (PMID 32321836, 2020).
Parkinson disease (continued). "LRRK2 mutations have emerged as the most prevalent and potentially treatable determinants of Parkinson's disease (PD)." (PMID 32148752, 2020). "Autosomal dominant missense mutations that hyperactivate the leucine-rich repeat protein kinase-2 (LRRK2) are a common cause of inherited Parkinson's disease and therapeutic efficacy of LRRK2 inhibitors is being tested in clinical trials." (PMID 32036294, 2020). "Mutations in leucine-rich repeat kinase 2 (LRRK2) are the most common cause of genetic forms of Parkinson’s disease (PD) known to date." (PMID 32975566, 2020). "Aside from its link to inflammation, LRRK2 has also been implicated in the activity of mitochondria, which are key subcellular organelles linked to Parkinson’s disease." (PMID 32293561, 2020). "Rab8a is one of several Rab GTPases that are substrates of leucine-rich repeat kinase 2 (LRRK2), a serine/threonine kinase that is linked to Parkinson's disease." (PMID 32017888, 2020). "The protein encoded by the LRRK2 gene is considered a potential target for therapies to treat Parkinson’s disease, and several drugs that inhibit this protein are being tested in clinical trials." (PMID 32057291, 2020). "LRRK2 is a Ser/Thr kinase that is associated with inherited and sporadic forms of Parkinson disease." (PMID 32969543, 2020). "Previous work has indicated that the PARK16 locus, which harbors the gene encoding for Rab29, is involved in Parkinson's, and that Rab29 operates in a common pathway with LRRK2." (PMID 33135724, 2020). "Mutations in the leucine‐rich repeat kinase 2 (LRRK2) gene are the most common cause of familial Parkinson's disease (PD)." (PMID 31821596, 2020). "The Parkinson’s disease (PD)-associated kinase Leucine-Rich Repeat Kinase 2 (LRRK2) is a crucial modulator of the autophagy-lysosome pathway, but unclarity exists on the precise mechanics of its role and the direction of this modulation." (PMID 32550012, 2020). "The Parkinson’s disease-associated Leucine-rich repeat kinase 2 (LRRK2) is a complex multi-domain protein belonging to the Roco protein family, a unique group of G-proteins." (PMID 32508578, 2020). "For example, the G2019S mutation in the LRRK2 gene, the gene most widely associated with Parkinson’s disease, has been studied in healthy controls." (PMID 32116848, 2020). "Recently, rare LRRK2 SNPs were confirmed as associated with either leprosy type-1 reactions or Parkinson ́s Disease." (PMID 32433683, 2020). "It has been 15 years since the Leucine-rich repeat kinase 2 (LRRK2) gene was identified as the most common genetic cause for Parkinson’s disease (PD)." (PMID 32523507, 2020). "Of note, mutations in one of these LRRK2 interactors, the phosphoinositide phosphatase Synaptojanin-1, have recently been associated with inherited forms of Parkinsonism." (PMID 32508578, 2020). "Mutations in the Leucine-rich repeat kinase 2 gene (LRRK2) have been linked to familial and sporadic Parkinson’s disease (PD)." (PMID 32123243, 2020). "LRRK2 (leucine-rich repeat kinase 2) has been demonstrated that its mutations are associated with Crohn’s disease, Parkinson’s disease, ulcerative colitis, and mycobacterial infections." (PMID 32987825, 2020). "PD patients with LRRK2 mutations show clinically typical parkinsonism with neuropathology such as substantia nigral degeneration and Lewy bodies." (PMID 32180132, 2020). "The upgraded pathogenic variants include LRRK2 rs34637584 associated with autosomal dominant Parkinson disease 8 and SPINK1 rs148954387 associated with hereditary pancreatitis, both identified in one European-descent participant each." (PMID 31797629, 2020). "Mutations in leucine-rich repeat kinase 2 (LRRK2) gene cause late-onset, autosomal-dominant forms of Parkinson’s disease (PD)." (PMID 32256311, 2020). "Mutations in leucine-rich repeat kinase 2 (LRRK2) are an established cause of inherited Parkinson's disease (PD)." (PMID 32434048, 2020).
Parkinson disease (continued). "Mutations in the gene encoding leucine-rich repeat kinase 2 (LRRK2) are common genetic risk factors for both familial and sporadic Parkinson’s disease (PD)." (PMID 33266247, 2020). "Leucine-rich repeat kinase 2 is a massive protein mutated in neurological patients with Alzheimer’s disease and Parkinson’s disease (PD)." (PMID 33291236, 2020). "Genome-wide association studies have identified dominant LRRK2 alleles that predispose their carriers to late-onset idiotypic Parkinson's disease (PD) and also to autoimmune disorders such as Crohn's disease." (PMID 32111741, 2020). "Asymptomatic carriers of leucine-rich repeat kinase 2 (LRRK2) gene mutations constitute an ideal population for discovering prodromal biomarkers of Parkinson’s disease (PD)." (PMID 32375873, 2020). "There is great interest in all aspects of LRRK2 biology because genome-wide association studies have identified many variants in this protein that predispose to late-onset Parkinson's disease." (PMID 32111741, 2020). "Here we identified by a PEP-scan approach a peptide of LRRK2, a Parkinson’s disease associated protein, interacting with the phosphatase PP1." (PMID 32790695, 2020). "Mutations in the LRRK2 gene are a major cause of Parkinson’s disease (PD), a common age-dependent neurodegenerative disorder characterized by neuronal damage in multiple brain regions and consequent motor defects." (PMID 32375042, 2020). "Among these, mutations in the Leucine-rich repeat kinase 2 (LRRK2) gene are currently recognized as the most prevalent monogenetic cause of Parkinsonism." (PMID 31664682, 2020). "Originally identified as a familial Parkinson’s disease (PD) risk gene, variations in LRRK2 are also associated with risk of idiopathic PD, inflammatory bowel disease and susceptibility to bacterial infections." (PMID 32210756, 2020). "A recent genetic study links the cocaine abuse to secondary Parkinsonism as a consequence of a potential gene-environmental interaction, namely a detected leucine-rich repeat kinase 2 (LRRK2) risk variant." (PMID 32545328, 2020). "Mutations in genes encoding the MT-interacting proteins Parkin, leucine-rich repeat kinase 2 (LRRK2), and α-syn indeed cause autosomal forms of parkinsonism." (PMID 33027950, 2020). "For LRRK2, most of the published information is for the Parkinson’s-causative mutations G2019S or I2020T, driven by Ddc-GAL4." (PMID 32321836, 2020). "In this study, we targeted the interaction between PP1 and LRRK2, a Parkinson’s disease (PD) associated protein." (PMID 32790695, 2020). "Here we report a patient, who developed Parkinsonism in young age after chronic cocaine use, in whom a homozygous LRRK2 risk variant was also detected." (PMID 31660902, 2019). "Mutations in leucine-rich repeat kinase 2 (LRRK2) and α-synuclein are known risk factors for Parkinson’s disease (PD)." (PMID 31685675, 2019). "For example, in Parkinson’s disease, wild type LRRK2 expression has been observed to cause mitochondrial fragmentation and increased levels of DRP-1." (PMID 30861027, 2019). "Mutations or overexpressions of LRRK2 gene are strongly associated with development of Parkinson's disease." (PMID 31814881, 2019). "Translating our findings into human cell lines, we find comparable molecular alterations in fibroblasts from Parkinson’s patients with the known pathogenic G2019S LRRK2 mutation." (PMID 30872638, 2019). "Genetic factors causing Parkinson’s disease have been identified, among which mutations in the LRRK2 gene, which encodes for a multidomain protein encompassing central GTPase and kinase domains, surrounded by protein-protein interaction domains." (PMID 31920513, 2019). "Mutations in the leucine-rich repeat kinase 2 (LRRK2) protein have been associated with Parkinson’s disease." (PMID 31216762, 2019).
Parkinson disease (continued). "Human genetics studies have linked LRRK2 as a major genetic contributor to familial and sporadic Parkinson’s disease (PD), a neurodegenerative movement disorder that inflicts millions worldwide." (PMID 30635421, 2019). "In Parkinson’s disease, mutations in the leucine-rich repeat kinase 2 (LRRK2) gene are a frequent genetic cause of the disorder, and it has also been suggested that EV-associated LRRK2 carries pathogenic-potential for the disease." (PMID 31911768, 2019). "LRRK2 is a kinase protein with its variants associated with multiple diseases including Parkinson’s disease (PD), IBD and cancer." (PMID 30670047, 2019). "Mutations in leucine-rich repeat kinase 2 (LRRK2) are a common cause of genetically inherited Parkinson’s Disease (PD)." (PMID 30609797, 2019). "The reported frequency of LRRK2 mutations varies widely; mutations are more common in familial Parkinson’s disease (5–6%) than in sporadic disease (∼1%)." (PMID 31324919, 2019). "Within this study we investigated the possible role of the Parkinson’s disease-linked LRRK2 in intracellular signalling and showed that LRRK2 plays a crucial role in insulin-dependent signal transduction." (PMID 30872638, 2019). "LRRK2 has been mainly associated with familial cases of Parkinson’s disease and has been known to play an important in innate immunity in the peripheral and central nervous system, especially in microglial inflammatory processes." (PMID 31035605, 2019). "The common causes of autosomal dominant forms of Parkinson’s disease are due to mutations in leucine-rich repeat Kinase 2 (LRRK2) and in VPS35 D620N." (PMID 30744021, 2019). "Membrane trafficking has emerged as central to the functions of leucine-rich repeat kinase 2 (LRRK2), which is associated with inherited and sporadic forms of Parkinson’s disease (PD)." (PMID 30640902, 2019). "Leucine-rich repeat kinase 2 (LRRK2) is a molecule associated with familial and sporadic Parkinson’s disease." (PMID 31555076, 2019). "The LRRK2 mutation in Parkinson disease showed an excellent motor response to STN DBS, with 46% reduction in the UPDRS-III score and more than 60% reduction in dopaminergic therapy." (PMID 30707228, 2019). "Mutations in the gene encoding for leucine-rich repeat kinase 2 (LRRK2) are a common cause of hereditary Parkinson's disease." (PMID 30709905, 2019). "As the population ages, it is likely that increasing numbers of LRRK2 relatives will develop Parkinson’s disease as a result of LRRK2 mutations, and the prevalence of this form of Parkinson’s disease will increase in the UK." (PMID 31324919, 2019). "This meta-analysis and systematic review suggests that patients with Parkinson disease who are carriers of LRRK2, GBA, and PRKN gene mutations show good motor advantages after STN DBS, comparable to patients with idiopathic Parkinson disease." (PMID 30707228, 2019). "LRRK2-associated Parkinson’s disease is clinically and neuropathologically similar to idiopathic Parkinson’s disease, also showing age-dependency and incomplete penetrance." (PMID 31920513, 2019). "Mutations in genes for both proteins (GBA1 and LRRK2) are associated with familial cases of Parkinson’s disease." (PMID 30654525, 2019). "Mutations in leucine‐rich repeat kinase 2 (LRRK2) gene have been pathogenically linked to Parkinson's disease, and pharmacological inhibition of LRRK2 is being pursued to tackle nigro‐striatal dopaminergic neurodegeneration." (PMID 31149340, 2019). "Six LRRK2 mutations have been pathogenically linked to Parkinson’s disease, the most frequent being the G2019S in the kinase domain." (PMID 31920513, 2019). "Further support for tau pathology as the neuropathological substrate of the parkinsonism observed in LRRK2 mutation carriers has come from the identification of progressive supranuclear palsy (PSP)-like tau inclusions observed in several cases." (PMID 31733655, 2019).